P2RX7 (purinergic receptor P2X 7)
Diseases named in the same sentence as P2RX7 in open-access papers (continued):
Sharing a sentence is not in itself a finding about the gene and the disease.
P2RX7 also shares sentences with these, for which no sentence is quoted: amyotrophic lateral sclerosis (22 papers); Stroke (21); prostate carcinoma (15); inflammatory bowel disease (13); chronic lymphocytic leukemia (12); ischemia (12); Huntington disease (11); infectious disease (11); non-small cell lung carcinoma (11); metabolic disease (9); myeloma (9); age-related macular degeneration (8); bacterial infection (8); bone cancer (7); Cerebral ischemia (7); cyst (7); lymphoma (7); experimental autoimmune encephalomyelitis (6); fibrosis (6); kidney disease (6); migraine (6); preeclampsia (6); Ureteral obstruction (6); basal cell carcinoma (5); brain tumors (5); dermatitis (5); diabetic nephropathy (5); dyslipidemia (5); emphysema (5); endothelial dysfunction (5).
A further 223 diseases each share a sentence with P2RX7 in 5 papers or fewer.